TNF (tumor necrosis factor)
Diseases named in the same sentence as TNF in open-access papers (continued):
Sharing a sentence is not in itself a finding about the gene and the disease.
tuberculosis (continued). "Higher values of T-cell associated mediators (IL-4, -5, -7, -13, -17, -12p70; RANTES/CCL5, TNF-α) and growth factors (PDGF, FGF, and TGF-β1) grouped together in participants with a tuberculosis dissemination score of zero." (PMID 31276515, 2019). "Despite these anti-mycobacterial features, TNFα directly promotes M. tuberculosis growth in human monocytes, and its cytotoxic character contributes to tissue damage and necrosis of TB lesions that in turn may contribute to organ dysfunction." (PMID 31739600, 2019). "These TNF-α cytokine networks help explain further the observation that anti-TNFα mAb treatment in RA patients with LTBI leads to dysfunction of CD8+ T cells or other T effectors, with consequence of reactivation of tuberculosis." (PMID 31080452, 2019). "Owing to the dramatic reduction of the incidence of tuberculosis because of widespread screening and treatment of LTBI before the initiation of TNF inhibitors, screening for LTBI before starting therapy with TNF inhibitor is recommended." (PMID 29975703, 2018). "TNF-α has been identified to play various roles in the immune and pathological responses in TB by preventing the reactivation of persistent tuberculosis, modulating the pulmonic expression of specific immunologic factors and limiting the pathological response of the host." (PMID 30583589, 2018). "Among these cytokines, tumor necrosis factor alpha (TNF-α) has a prominent role in the defense of and pathological responses to tuberculosis." (PMID 30588415, 2018). "In Turkey, another mediterranean country, a retrospective study in an anti-TNF-treated IBD population showed a prevalence of latent tuberculosis of 59% and, during the follow-up period, a prevalence of 5% of active tuberculosis." (PMID 29075289, 2017). "Elsewhere, differences in IFNγ+TNFα+IL-2+, TNFα-single positive CD4+ T cells or a general increase in multi-cytokine producing T cells expression were observed between tuberculosis patients and contacts." (PMID 28241036, 2017). "Increased cytokine secretion was subsequently observed with vimentin stimulation of sarcoidosis PBMCs vs. tuberculosis PBMCs (IFN-γ: 396.6 pg/mL vs 0.1 pg/mL, p = 0.0009; TNF-α: 1139 pg/mL vs 0.1 pg/mL, p<0.0001)." (PMID 28114394, 2017). "The aim of this paper was to assess the tuberculosis (TB) risk in patients with rheumatic diseases receiving non-anti-TNF-targeted biologics." (PMID 28659665, 2017). "In rheumatology practice, it is common practice to screen for tuberculosis, HBV, HCV, HIV and varicella zoster virus antibodies prior to the initiation of anti-TNF-α therapy in patients." (PMID 29065914, 2017). "Tumor Necrosis Factor inhibitors (TNFi) have dramatically improved the outlook for patients with inflammatory arthritides and bowel disease (IBD), but are associated with increased infection risks, including tuberculosis (TB)." (PMID 29121953, 2017). "Moreover, the epidemiology of TB and the role of different cytokines (TNF-α, IL-6, IL-17, IL-12, and IL-23) in immune response against Mycobacterium tuberculosis (MTb) were reviewed." (PMID 28659665, 2017). "Interestingly, CD4 T cells coexpressing IFN-γ and TNF-α and harboring a phenotype of effector-memory response were associated with active tuberculosis in HIV-uninfected and HIV-infected TB patients." (PMID 28759590, 2017). "Additionally, M. tuberculosis regulates IFN-γ and TNF-α in human T cells through miR-144* and it is upregulated in the blood samples of TB patients." (PMID 27536558, 2016). "Immunological disruptions within this delicate balance, such as CD4+ T-cell and tumor necrosis factor (TNF) neutralization, can lead to increased tuberculosis pathology." (PMID 27462092, 2016). "Patients who develop an active tuberculosis infection during tumor necrosis factor (TNF) inhibitor treatment typically discontinue TNF inhibitor and receive standard anti-tuberculosis treatment." (PMID 27101309, 2016).
tuberculosis (continued). "On the one hand, patients with active tuberculosis have a significantly higher production of cytokines IFN-γ and TNF-α from MAIT cells in responding to ex vivo BCG stimulation but not to E. coli stimulation, as compared to healthy control subjects." (PMID 28066410, 2016). "Methotrexate (MTX), tumor necrosis factor (TNF) inhibitor administration, and new tuberculosis cases were determined during our study period." (PMID 26047099, 2015). "Our study evaluated the mRNA and cell surface expression of TLR2 and TLR4; iNOS expression; and the production and expression of IL-12, IFN-γ, TNF-α, IL-17, IL-10 and TGF-β in pulmonary tuberculosis patients during anti-tuberculosis treatment." (PMID 24558401, 2014). "In those with active tuberculosis, >17.3% of PPD-specific CD4+ TNF-α-only-secreting cells were CD45RA−CCR7−CD127−, and this phenotype was therefore strongly associated with activated infection." (PMID 23966657, 2013). "The frequency of PPD-specific CD4+ IFN-γ only, TNF-α only, and IFN-γ/TNF-α-dual-secreting cells was higher in active tuberculosis compared with latent tuberculosis infection (P = .003.002, and .002, respectively)." (PMID 23966657, 2013). "In active tuberculosis, compared with latent tuberculosis infection, a higher percentage of CD4+ cells secreting IFN-γ-only or TNF-α-only in response to PPD and RD1-peptides were TEFF." (PMID 23966657, 2013). "IFN-γ, TNF-α, and VEGF would be an immune response markers of adjacent tissue in response to tuberculosis." (PMID 22889060, 2012). "Given the rapidly expanding list of inflammatory conditions for which tumor necrosis factor-α inhibitors are receiving FDA approval, the incidence of tuberculosis in this patient population has increased." (PMID 23304607, 2012). "TNF-α as a pro-inflammatory cytokine plays a key role in host defense against tuberculosis (TB)." (PMID 22737473, 2011). "The control of tuberculosis (TB) requires clearly delineated Th1 responses (IL-12, IFN-γ, and TNF-α) and, to a lesser extent, Th17 responses (IL-17 and IL-23)." (PMID 19636364, 2009). "The BALfluid TNF-α, IL1β, and TNF-α receptor levelswere higher in patienst with cavitated tuberculosis, but there wasno such difference in serum levels." (PMID 17497033, 2007). "No cases of tuberculosis or viral hepatitis replication were observed among patients having received anti-TNFα therapy." (PMID 40170787, 2025). "Thus, key cytokines and chemokines such as IL-1β, IL-6, IL-8, TNF-α and IFN-γ play an important role in the pathogenesis of both COPD and tuberculosis." (PMID 40141021, 2025). "The incidence of tuberculosis (TB) was analyzed across various TNF-α blocker medications in patients, both with and without LTBI treatment." (PMID 40711067, 2025). "In the same line, it has been reported that protection against pox-virus, Leishmania major malaria, and tuberculosis may also be T-cell-mediated, with various functions such as IFN-γ, IL-2, TNF-α, and granzyme B being potentially involved." (PMID 41012118, 2025). "Like tuberculosis patients, the CD patients in the TU/ACU study had elevated IFNγ, IL-17 and TNFα." (PMID 38415011, 2024). "TNF-α, along with IFN-γ, play a significant role in the immunological and pathological reactions to tuberculosis (TB) via inhibiting the recurrence of TB and controlling the pathogenic response of the immune system and pulmonic expression of certain immunologic components." (PMID 38790916, 2024). "Still focusing on infectious disease, high levels of TNF-α were detected in participants from this group, which is in line with the role of this pro-inflammatory cytokine in the pathogenesis of immune-mediated diseases such as HIV and tuberculosis." (PMID 39328992, 2024). "TNFα and IFN γ are crucial for tuberculosis granuloma formation." (PMID 38265349, 2024). "While for anti-TNFα treatments, tuberculosis risk is a relevant issue, in the OCTAVE trials no cases of tuberculosis have been reported using Tofacitinib." (PMID 39685645, 2024).
tuberculosis (continued). "Our findings may be one of the reasons explaining the role of IL-32 in controlling the immune response of tuberculosis, indicating that IFN-γ/IL-32/TNF-α signaling axis may play an important role in the pathogenesis of tuberculosis." (PMID 38803498, 2024). "The CD patients with MAP infection in the TU/ACU study had elevated (IFNγ), TNFα and IL-17A like tuberculosis patients, but they did not have elevated IL-2, IL-5, IL-10 and GM-CSF typically reported in tuberculosis patients." (PMID 38415011, 2024). "Active tuberculosis or other serious infections, such as sepsis and opportunistic infections, as well as moderate-to-severe heart failure (NYHA-class III/IV), are contraindications for TNF-α inhibitors." (PMID 37568441, 2023). "Importantly, tuberculosis (TB) must be ruled out prior to starting TNF-alpha inhibitor therapy as they can increase the risk of disseminated TB." (PMID 37294447, 2023). "A recent network meta-analysis assessed the risk of malignancies (such as non-melanoma skin cancer and lymphoma), tuberculosis, and infections in RA patients with different TNF-α therapies." (PMID 37568441, 2023). "For that, circulating levels of TNFα and SAA were measured in the plasma of a cohort of patients with active tuberculosis compared to those detected in healthy controls of unknown IGRA status or for IGRA+ (latent tuberculosis infection, LTBI) individuals." (PMID 37153579, 2023). "Among the various cytokines, pro-inflammatory cytokines (TNF-α, IL-6, and IL-1β), and Th1 cytokines (IL-12, IFN-γ, and IL-2) are known to confer significant protection against tuberculosis, while anti-inflammatory cytokines (IL-10 and TGF-β) and type-I interferons (IFN-β) confer susceptibility." (PMID 35832818, 2022). "Hence, TNF depletion in M. tuberculosis-infected mice represents an additional model to investigate drug distribution by MALDI-MS imaging to mimic reactivation of TB in latently infected individuals under anti-inflammatory treatment." (PMID 34871095, 2022). "Among them, only vimentin stimulation induced an IFN-γ/TNF-α-based inflammatory response from sarcoidosis PBMCs; interestingly, IFN-γ and TNF-α were significantly higher in sarcoidosis-derived PBMCs than in tuberculosis-derived and healthy control-derived PBMCs." (PMID 36148452, 2022). "Our results showed a non-significant difference in the incidence of tuberculosis following treatment with anti-TNFα agents (OR: 2.55, 95% CI: 0.40–16.23, p = 0.32)." (PMID 34790122, 2021). "After positive IGRA conversion, none of the six converters developed active tuberculosis while maintaining non-TNF inhibitor therapy (median 6.8 months, range 0.4–32.1 months)." (PMID 34095175, 2021). "Etanercept, an inhibitor of tumor necrosis factor α (TNF-α) involved in the formation and maintenance of granuloma, may help treat tuberculosis." (PMID 33603720, 2020). "Discussion and conclusion: Since the level of serum TNF-α is higher in patients with pulmonary tuberculosis than in individuals without it, the measurement of TNF-α levels can be useful as a probable marker for the diagnosis of tuberculosis." (PMID 30588415, 2018). "TNF-α blockade in patients with active tuberculosis and in the PPD positive control group did not interfere with the formation of granuloma, but modulated some of the cytokines analyzed." (PMID 29543912, 2018). "As few patients with UC were treated with anti-TNF-α agents in this study, none of them experienced hepatitis B or tuberculosis reactivation." (PMID 30373275, 2018).
tuberculosis (continued). "It is also important to note that combination of the Th1 cytokines [IFN-γ, TNF-α, IL-2 and IL-12(p70)] showed an excellent predictive power in discriminating between cultures-confirmed pulmonary-tuberculosis patients against culture-negative individuals." (PMID 31086619, 2018). "Mycobacteremic patients had lower absolute counts of IL-6+ monocytes compared with non-mycobacteremic tuberculosis patients in unstimulated samples and lower absolute counts of both IL-6+ and TNF-α+ monocytes in response to LPS." (PMID 28369200, 2017). "Although there is still considerable controversy over what kind of immune response is required for an effective vaccine against tuberculosis, the consensus view is that a shift towards a Th1 profile should be protective, with increased production of IFN-γ, TNF-α and IL-2." (PMID 28522873, 2017). "We speculate that patients in the LTBI group who have a higher TNF-α–only TEFF response, which overlaps most with the tuberculosis group, may be more likely to progress to tuberculosis." (PMID 28329119, 2017). "HIV-tuberculosis patients had higher supernatant concentrations of CSF-3, IFN-ɣ, and IL-1-receptor-antagonist (IL-1RA) and lower concentrations of CSF-2, IL-12p40, IL-1β, IL-6, and TNF-α." (PMID 28369200, 2017). "The range of the proportions of TNF-α–only TEFF cells in the recently acquired LTBI group in the current study was far wider than in the remotely acquired LTBI group and is similar to that in the tuberculosis patient group." (PMID 28329119, 2017). "One Korean report showed 3 patients resumed TNF inhibitors before the completion of tuberculosis treatment and 1 patient restarted TNF inhibitors one month after tuberculosis treatment completion and relapse did not occur in the mean 32 months of duration." (PMID 27101309, 2016). "Five patients among them restarted anti TNF treatment after a mean of 14 months of tuberculosis diagnosis without relapse within those months or the following period." (PMID 27101309, 2016). "The clinical features of resumers and non-resumers of TNF inhibitors were compared and the outcomes of tuberculosis were surveyed individually." (PMID 27101309, 2016). "On the other hand, no new case of tuberculosis with abatacept after failure to anti-TNF-alpha was registered in the ARRIVE study." (PMID 27974925, 2016). "The consensus of the Tuberculosis Network European Trialsgroup states delay for TNF inhibitor as long as possible in the absence of specific clinical trials." (PMID 27101309, 2016). "In France, 2 AS patients from a national registry who developed active tuberculosis while receiving infliximab recommenced TNF inhibitor without relapse, were reported by a postal questionnaire." (PMID 27101309, 2016). "Indeed, the levels of TNF-α have been shown to be higher in patients with tuberculosis (TB)." (PMID 25295870, 2014). "The frequencies of PPD- and RD1-peptide-specific CD8+ IFN-γ-only producing cells were significantly higher in active tuberculosis than in latent tuberculosis infection (P = .017 and .016, respectively), as was the frequency of CD8+ PPD-specific cells secreting both IFN-γ and TNF-α (P = .013)." (PMID 23966657, 2013). "In this study, TNF-α-single-positive Mycobacterium tuberculosis-specific CD4+ T cells were preferentially detected in active tuberculosis disease rather than in latent infection." (PMID 23638039, 2013). "We can infer the absence of a protective role for TNF-α-single-positive T cells from a recent study of tuberculosis." (PMID 23638039, 2013). "We have found cytokines of predominantly myeloid origin (IL-6 and TNF-α) to be consistently elevated in patients with tuberculosis IRIS, compared with those who did not develop IRIS." (PMID 23097584, 2013). "For example, a tuberculosis vaccine based on modified vaccinia virus Ankara expressing antigen 85A, and the Yellow Fever vaccine induced T cells producing combinations of IFN-γ, TNF-α, IL-2, and MIP-1β." (PMID 22412866, 2012).
tuberculosis (continued). "This is further supported by the observation that, in a large series of validated tuberculosis cases among patients using TNF-α antagonists, initial TST was negative in 67% of the patients." (PMID 22709461, 2012). "However, while there was decrease in TNF-α production in PPD stimulated cultures, the INF-γ production in unstimulated cultures was higher in co-infected patients than in patient only with tuberculosis." (PMID 22925731, 2012). "The 38 RA patients who were prescribed TNF-α antagonists, 40 RA patients who were not considered for TNF-α antagonist use, 30 rheumatology patients with a history or new diagnosis of tuberculosis, 23 leprosy patients, and 41 healthy controls were studied." (PMID 22709461, 2012). "We therefore evaluated whether adjunctive inhibition of tumor necrosis factor alpha (TNF-α)–a key cytokine in host responses against TB–could hasten bacterial clearance in a mouse strain that develops necrotic lesions in response to Mycobacterium tuberculosis infection." (PMID 22761866, 2012). "We hypothesize that one such factor, IL-4, a cytokine whose expression appears to correlate with a poorer prognosis after M. tuberculosis infection when combined with TNF-α, may worsen TB-related pathology, possibly by biasing cell death towards necrosis instead." (PMID 21253484, 2011). "In this study, we have shown that Ag85A and ESAT-6 are antigens able to differentiate pulmonary, extra-pulmonary and tuberculosis patients undergoing chemotherapy from healthy individuals by IFN-γ production and pulmonary and under treatment patients from extra-pulmonary TB by TNF-α." (PMID 21253450, 2011). "Two patients treated with rituximab and no patients treated with anti-TNF agents developed tuberculosis." (PMID 21745378, 2011). "Circulating serum levels of CXCL8 and TNFα were raised in all tuberculosis patients, while CCL2 levels were not." (PMID 16001981, 2005). "Research has extensively documented that cytokines such as IFN‐γ, IL‐2, TNF‐α, and IL‐17 play crucial roles in combating M. tuberculosis and in BCG‐induced protection against TB." (PMID 40170749, 2025). "Following standard anti-TB therapy, we evaluated the level of dual (IFN-γ + TNF-α+) cytokine-producing CD4 + T cell activation and proliferation markers from M. tuberculosis-specific, smear-negative PTB patients." (PMID 40901996, 2025). "In the DS tuberculosis model, double immunization with TB/FLU-06E at the start of the HR therapy resulted in a significantly higher level of total spleen-derived cytokine-producing CD4+ and CD8+ Tem cells (CD44+ CD62L-), with a markedly higher proportion of IFN-γ and IFN-γ,TNF-α producing cells." (PMID 39065554, 2024). "Mtb-HAg can also distinguish TB and latent tuberculosis infection (LTBI) by stimulating the production of different TNF-α and IFN-γ levels in human peripheral blood T cells." (PMID 38741147, 2024). "Despite in patients from registry it was shown that the incidence of tuberculosis appears higher among users of anti-TNF than among users of other non-anti-TNF biologics, anti-TNF drugs can be employed with a satisfactory safety profile in patients with risk of LTBI." (PMID 38979406, 2024). "This study has demonstrated participant uncertainty about the need for tuberculosis screening in patients treated with biologics other than TNF-a inhibitors, for which there has been little research and there are fewer available guidelines than for TNF-a inhibitors." (PMID 39356910, 2024). "IRIS has been recognized during tuberculosis (TB) therapy, especially in patients newly initiated on antiretroviral therapy for HIV or those taken off immunosuppressives such as tumor necrosis factor-alpha inhibitors." (PMID 37273292, 2023). "A previous study also found out that in tuberculosis, as a chronic infection, the expression of CD244 and then LncRNA-GSTT1-AS1, known as LncRNA-CD244, increased in CD8+ T cells, which led to decreased IFN- and TNF- production and impaired immune response to infection." (PMID 37634081, 2023).